MCL1 (MCL1 apoptosis regulator, BCL2 family member)
Diseases named in the same sentence as MCL1 in open-access papers (continued):
Sharing a sentence is not in itself a finding about the gene and the disease.
lymphoma (142 papers, 2006 to 2026). A malignant (clonal) proliferation of B- lymphocytes or T- lymphocytes which involves the lymph nodes, bone marrow and/or extranodal sites. "In the dominant inheritance model, the MCL1-TT and MCL1 (TG + GG) genotypes were highly related, with odds of 1.98 (95% CI = 1.09–2.51) and 1.28 (1.03–1.61) times the increase in lymphoma risk, respectively." (PMID 36831357, 2023). "By contrast, the removal of BCL-XL or MCL-1 (even just one allele of Mcl-1) greatly delayed lymphoma development in Eμ-Myc mice." (PMID 37567974, 2023). "Whilst performing CRISPR/Cas9 whole genome knockout (KO) screens to identify factors that confer resistance to MCL-1-targeting BH3-mimetics in Eμ-Myc lymphoma cells, we additionally identified loss of the apoptotic effector BAX as a top hit." (PMID 36755070, 2023). "When these mouse lymphoma cells are transplanted into recipient mice, loss of even one allele of Mcl-1 can invoke tumour regression, demonstrating their high dependence on MCL-1 for sustained survival and tumour expansion." (PMID 36755070, 2023). "Mcl-1 has been implicated as an apoptotic regulator in Eμ-Myc–driven lymphomas and is regulated by P-TEFb." (PMID 37882668, 2023). "In the case of the dominant inheritance model, a strong association of MCL1-TT vs. MCL1-(TG + GG) genotypes was observed, which leads to increased lymphoma patient susceptibility." (PMID 36831357, 2023). "Our work complements these findings and reveals that loss of BAX is the most potent resistance factor for MCL-1 inhibition in lymphoma, and also that such resistance can be overcome by treatment with standard-of-care chemotherapeutic drugs." (PMID 36755070, 2023). "The MCL1-TG genotype was significantly related to higher lymphoma patient susceptibility in the codominant model, whereas the MCL1-GG genotype was not." (PMID 36831357, 2023). "It has been shown that high levels of MCL-1 expression are required for B-lymphoma cell survival and correlate with high-grade lymphoma, suggesting an association between high levels of MCL-1 expression and progressive disease." (PMID 37601693, 2023). "In line with this, it has been reported that NQ triggers cell death in L5178Y murine lymphoma cells and SA causes apoptosis by downregulation of the anti-apoptotic factors MCL-1/BCL-2." (PMID 35684504, 2022). "In the vavP-Mcl-1 transgenic mice, overexpression of Mcl-1 in all hematopoietic compartment predisposes these mice to late onset lymphoma with a phenotype resembling hematopoietic stem cells/progenitor cells expressing both B- and T-cell markers." (PMID 34336857, 2021). "Several studies have shown that high BCL-2/MCL-1 or BCL-2/BCL-XL ratios are associated with sensitivity to BH3 mimetics in various types of lymphoma." (PMID 32290241, 2020). "Loss of one MCL-1 allele almost abrogated MYC-driven-lymphoma development owing to a reduction in lymphoma initiating pre-B-cells." (PMID 32549409, 2020). "Transgenic modelling of increases in pro-survival proteins has mostly been limited to the haematopoietic systems where elevation of Bcl2, Mcl1 or Bclx predisposes to lymphoma development, albeit with long latency and incomplete penetrance." (PMID 29769323, 2018). "We report that there was marked selection against Mcl-1 gene loss during c-MYC-driven lymphoma development and a delay in tumor onset." (PMID 26962682, 2016). "To explore the impact of B cell-restricted deletion of one or both allele(s) of Mcl-1 on c-MYC-driven lymphoma development, we generated Eμ-Myc mice with one or both Mcl-1 alleles flanked by loxP sites (hereafter called Mcl-1fl/+ or Mcl-1fl/fl, respectively)." (PMID 26962682, 2016).
lymphoma (continued). "In an Akt-driven, Eμ-Myc lymphoma mouse model, translational regulation of Mcl-1 by mTOR has been implicated in promoting lymphomagenesis." (PMID 23431463, 2013). "While still correlative at this point, our data suggest that inhibition of BCL-xL along with inhibition of BCL-2 and MCL-1 may be required for inducing response in a subset of patients with high-risk lymphomas." (PMID 29269870, 2017). "However, only ~50–60% of the two floxed Mcl-1 alleles had been recombined in the lymphomas from the Eμ-Myc;CD19-Cre;Mcl-1fl/fl mice." (PMID 26962682, 2016). "Therefore, B-lymphoid-restricted loss of one allele of Mcl-1 can substantially delay pre-B/B-lymphoma development in Eμ-Myc mice." (PMID 26962682, 2016). "However, lymphoma cells could upregulate MCL-1 and MYC upon venetoclax treatment, which might cause resistance to venetoclax." (PMID 38918775, 2024). "In this study, we report the presence of residual drug-tolerant persister (DTP) and resistant lymphoma cells remaining within a highly immunogenic tumor microenvironment (TME) induced by the MCL-1 inhibitor (MCL-1i) S63845." (PMID 41680300, 2026). "Consistent with both lymphoma models, the expression of Bim and Mcl-1 increased in response to ixazomib treatment of primary CLL cells (right)." (PMID 40701968, 2025). "Beyond VEGF, SRPK1 inhibition alters the splicing of MCL1/BIN1/BCL2 to produce pro-apoptotic isoforms in cholangiocarcinoma and causes stress-associated cell death in lymphoma." (PMID 41551143, 2025). "Following this, we detected a tenfold increased expression of the alternative anti-apoptotic MCL1 in healthy CD34 + cells compared to lymphoma cell lines, protecting the progenitor cells from long-lasting abolishment of BCL2 by VEN." (PMID 39531065, 2025). "It is well known that, in most lymphomas, overexpression of the biomarkers Bcl-2 and Mcl-1 is promoted." (PMID 39769118, 2024). "Studies have pointed toward the development of more selective protein inhibitors in the BCL-2 family, including Bcl-2 and Mcl-1, to counteract the progression of lymphomas in patients." (PMID 39769118, 2024). "These lymphoma lines were treated in culture with a range of concentrations of the BH3-mimetic drugs S63845 (MCL-1 inhibitor) and ABT-737 (inhibitor of BCL-2 + BCL-XL + BCL-W)." (PMID 37567974, 2023). "As such, six MCL-1 inhibitors have entered into stage 1 clinical trials for relapsed/refractory lymphomas, AML and multiple myeloma." (PMID 36755070, 2023). "In the codominant inheritance model, it was found that the variation in the MCL1-TG genotype was substantially related to the odds of lymphoma by 1.93 (95% CI = 1.08–3.43) and 1.35 (1.03–1.77) times more in cases than controls." (PMID 36831357, 2023). "A study of mouse lymphoma models knocked in with human MCL-1 showed that S63845 was efficacious at tolerable doses." (PMID 37601693, 2023). "A similar finding was reported in a murine double-hit lymphoma model, in which inhibiting MCL-1 protein synthesis by homoharringtonine and concomitant Noxa induction by bortezomib reduced tumor growth and increased survival significantly." (PMID 37601693, 2023). "The magnitude of the enitociclib pharmacodynamic effect is demonstrated by a sustained reduction and near clearance of Myc and Mcl-1 proteins in MYC-expressing lymphoma cell lines in vitro and in vivo." (PMID 37882668, 2023). "This reveals that whilst BAX is the primary mediator of the apoptotic response in Eμ-Myc lymphoma cells following exposure to MCL-1-targeting BH3-mimetic drugs, BAK does play an important complementary role in this apoptotic process." (PMID 36755070, 2023).
lymphoma (continued). "We examined the responses of sgTfap4/Eμ-MYC/Cas9 and sgControl/Eμ-MYC/Cas9 lymphoma cell lines to the BH3 mimetic drugs ABT-199/Venetoclax or S63845 that inhibit BCL-2 or MCL-1, respectively." (PMID 36894688, 2023). "A higher risk of lymphoma, notable NHL, was shown to be related to variations in the antiapoptotic genes BCL2-938 C > A, MCL1-rs9803935 T > G, survivin-rs17882231 G > C, and BIRC5-rs9904341 G > C, particularly among men aged more than 45 years." (PMID 36831357, 2023). "The C allele in BIRC5, G allele in MCL1, and the G allele in BIRC5 were all substantially associated with an elevated risk of lymphoma, with the exception of the BCL-2-A allele." (PMID 36831357, 2023). "Eμ-MYC lymphoma cells are generally dependent on the pro-survival BCL-2 family member MCL-1 for their sustained survival." (PMID 36894688, 2023). "ABT199/venetoclax inhibition of BCL-2 has been reported to result in compensatory upregulation of the anti-apoptotic MCL1 in lymphoma and neuroblastoma cell lines." (PMID 35154579, 2022). "Of note, we identified one BCL-2 expressing lymphoma cell line which is fully resistant to MCL-1 inhibitor treatment, but sensitive to venetoclax." (PMID 35961968, 2022). "Pharmacologically induced Noxa protein expression in lymphoma cells has been shown to reduce Mcl1 protein expression and thus increase the vulnerability of lymphoma cells in vitro and in vivo." (PMID 35897737, 2022). "The CDK9 inhibitor AZD4573 was also found to indirectly down-regulate BFL-1 in conjunction with MCL-1 in BH3-mimetic–resistant lymphoma cell lines and lead to in vivo tumour regressions in BFL-1+ DLBCL PDX models." (PMID 35900226, 2022). "Third, IACS‐010759 showed synergy with BH3‐mimetic compounds that inhibit either BCL2 or Mcl‐1, allowing context‐dependent killing of lymphoma cell lines." (PMID 34632715, 2022). "With the notable exception of Mcl1, we observed a global upregulation of pro-survival factors in murine lymphomas induced by FYN-TRAF3IP2." (PMID 34140493, 2021). "Consistently, non-pharmacological inhibition of PP2A prevents MCL1 protein dephosphorylation at Thr-163/Ser-159 in the PEST region and dramatically reduces MCL-1 protein levels in MCL1-amplified lymphoma cells." (PMID 34638252, 2021). "In lymphomas, MCL1 dependence is likely inherited from the normal B cell counterpart and by being within the microenvironment of the lymph node compartment." (PMID 33670870, 2021). "Inhibition of CDK9 by selective inhibitors (e.g., AZ5576) or by genetic knockdown negatively regulated MYC and MCL-1 expression, and induced apoptosis in primary and transformed cells from this lymphoma, providing an attractive therapeutic strategy." (PMID 34041038, 2021). "EVs derived from lymphoma cells were shown to express c-Myc, Bcl-2, Mcl-1, CD19, and CD20 and stimulate angiogenesis by delivering angiogenic proteins, including VEGF." (PMID 33805807, 2021). "In a murine lymphoma model, blockade of mTORC1 by rapamycin downregulated Mcl-1 translation and resulted in rapid apoptosis." (PMID 34675258, 2021). "Overexpression of MCL-1 greatly accelerates the development of lymphoma driven by the oncogene c-MYC." (PMID 33883020, 2021). "In line with this, the overexpression of Mcl-1 dramatically accelerated the onset of lymphoma developed in the Eμ-Myc tumor model and were resistant to in vivo treatment using cyclophosphamide." (PMID 34336857, 2021). "The potential role of MCL-1 in lymphoma pathogenesis was demonstrated in transgenic mouse models in which MCL-1 transgenic mice developed B-cell lymphomas at high frequency." (PMID 32290241, 2020). "In cancer, not only has the MCL-1 protein been shown to regulate cell survival in myeloid and lymphoid cancers including MM, AML and NHL, but MCL1 amplifications have been found in >10% of solid tumor cancer types." (PMID 32131385, 2020).
lymphoma (continued). "Activated T cells in the microenvironment can produce cytokines such as IL-4 and IL-21, which can stimulate CD40 on lymphoma cells and increase the expression of MCL1, BCL-XL, and BFL1." (PMID 33292251, 2020). "MCL-1 has been identified as a resistance factor for venetoclax in multiple studies, indicating that survival of lymphoma cells can be mediated by both BCL-2 and MCL-1." (PMID 33308268, 2020). "This link between c-MYC-driven cancers and a dependency on MCL-1 was confirmed by genetic studies, where heterozygous deletion of MCL-1 resulted in diminished growth of c-MYC-driven lymphomas." (PMID 33308268, 2020). "In 2006, TW-37 was developed as a small molecule inhibitor of Bcl-2, Bcl-XL, and Mcl-1 and was shown to have anti-cancer activity in lymphoma cells." (PMID 32257914, 2019). "Previous genetic studies have shown that the development of B-lymphoid tumors in Eμ-Myc mice is critically dependent on expression of pro-survival MCL-1 and it is dispensable for sustained growth of fully malignant lymphoma cells in transplant recipients." (PMID 30975981, 2019). "Together, these data provide evidence that OTSSP167 treatment reduces Mcl1 protein levels, thereby sensitizing the lymphoma cells to venetoclax." (PMID 31740676, 2019). "To assess selectivity in a cellular context, we tested (Ra)-7 in Eμ-Myc lymphoma cell lines stably expressing the prosurvival Bcl-2 proteins Mcl-1, Bcl-2, Bcl-xL, Bfl-1/A1, or Bcl-w." (PMID 30559424, 2018). "Pharmacologic induction of NOXA, using the histone deacetylase inhibitor panobinostat, decreased MCL1 protein abundance and increased lymphoma cell vulnerability to BCL2 inhibitors in vitro and in vivo." (PMID 30404918, 2018). "In vivo inhibition of MCL1 using the small-molecule inhibitor UMI-77 also sensitized lymphoma cells to S55746 in a xenograft mouse model, resulting in an increase in caspase 3 cleavage and apoptosis." (PMID 30404918, 2018). "Unlike BCL-2 and BCL-X, which are overexpressed in a subset of MCL, MCL-1 expression is typically low in this lymphoma." (PMID 30671383, 2018). "mTORC1 inhibition in lymphomas dependent on the activation of this pathway resulted in decreased translation of Mcl-1 mRNA and induction of apoptosis." (PMID 28881582, 2017). "Down-regulation of Mcl-1 has shown tumor growth inhibition in colon, lung, ovarian cancer cells and lymphoma cells by inducing apoptosis." (PMID 29254209, 2017). "Very importantly, we observed that the reduction in Mcl-1 expression upon a Low CHO diet was sufficient to significantly sensitize lymphoma-bearing mice to ABT-737 induced death." (PMID 27689327, 2016). "Taken together, these results indicate that the Mcl-1 decrease observed in vivo in lymphoma-bearing mice fed with a Low CHO diet is mediated, at least in part, by the AMPK/mTOR control of its translation." (PMID 27689327, 2016). "We recently established that reducing the food intake of the mice by 25% (caloric restriction, CR) reduces Mcl-1 expression and sensitize lymphoma-bearing mice to BH3-mimetics." (PMID 27689327, 2016). "We established that a 25% reduction in CHO was sufficient to significantly reduce Mcl-1 expression in lymphoma cells." (PMID 27689327, 2016). "Altogether our data indicate that carbohydrates are the main macronutrients involved in the diet-induced reduction of Mcl-1 expression in B cells of lymphoma-bearing mice." (PMID 27689327, 2016). "Overall, we established that a short-term reduction of carbohydrate intake represents an innovative and safe way to reduce the expression of Mcl-1, a very important oncogenic protein in lymphoma cells, thereby sensitizing them to targeted chemotherapy." (PMID 27689327, 2016). "Western blot analysis revealed that many lymphomas from Eμ-Myc;CD19-Cre;Mcl-1fl/+(3/3 tested) and Eμ-Myc;CD19-Cre;Mcl-1fl/fl mice (2/3 tested) retained MCL-1 expression, but its levels were significantly lower than in lymphomas from Eμ-Myc control mice." (PMID 26962682, 2016).
lymphoma (continued). "In conclusion, our findings demonstrate that MCL-1 is critical for the survival of c-MYC overexpressing lymphoma-initiating cells and hence for development of lymphoma." (PMID 26962682, 2016). "To test the B-cell intrinsic requirement for endogenous MCL-1 in lymphoma development, we conditionally deleted Mcl-1 in B-lymphoid cells of Eμ-Myc transgenic mice." (PMID 26962682, 2016). "Here we report on the ability of a Low CHO diet to reduce Mcl-1 protein expression and to sensitize lymphoma cells to BH3-mimetics." (PMID 27689327, 2016). "Supporting this, other compounds that target mTOR pathway were also described to inhibit Mcl-1 at a translational level in lymphomas." (PMID 26110568, 2015). "To that end, we also demonstrate favorable single agent activity of obatoclax in cell lines and models of murine lymphoma in vitro and in vivo, which correlate with Mcl-1-dependent cell survival." (PMID 26231047, 2015). "Systemic treatment of mice bearing Tsc2+/- Em-myc lymphomas (whose cells depend on Mcl-1 for survival) with obatoclax conferred a survival advantage compared to vehicle alone (median 31 days vs 22 days, respectively; p=0.003)." (PMID 26231047, 2015). "The cross-linked BH3 peptide is capable of binding selectively to MCL-1 with an affinity comparable to that of NOXA (in the nM range) and it can induce death in a lymphoma cell line." (PMID 25970783, 2015). "Of note, mice overexpressing Mcl-1 under the Vav-gene promoter developed lymphomas with a multipotent stem or progenitor cell phenotype at high frequency, and murine HSPCs overexpressing Mcl-1 showed increased colony forming potential." (PMID 23180554, 2013). "A potential candidate mediating this effect is the anti-apoptopic protein Mcl1, which can be stabilised by Usp9x, at least in lymphoma and cultured cell lines." (PMID 23861879, 2013). "Altogether, these data propose that targeting Mcl-1 with microRNAs such as miR-29 represents a potential tool to constrict tumor growth of Mcl-1 positive lymphomas." (PMID 23431463, 2013). "Using Jurkat T lymphoma cells as a cell model, we examined protein translation and Mcl-1 levels in response to IR." (PMID 23402580, 2013). "For example, c-Myc, cyclin D1 and Mcl-1 were quickly down-regulated in lymphoma cells when cap-dependent translation was blocked." (PMID 23402580, 2013). "Transgenic mice expressing an MCL1 transgene in lymphoid tissues develop lymphoma after a long latency." (PMID 23482333, 2012). "Lymphoma cells in vitro acquired resistance after long-term exposure ABT-737 due to up-regulation of Mcl-1 and A1." (PMID 21915275, 2011). "Within lymphoma, Mcl-1 is expressed more abundantly in large (centroblasts) than small cells (centrocytes) and its expression is associated with higher proliferation and worse prognosis." (PMID 19220884, 2009). "Some of these events are specifically related to lymphomas, such as in case 5, which includes nine single-nucleotide events associated with lymphomas, e.g., the p.P925T missense variant in EP300 (COSV54337074), or events in MCL1 and PTPN13." (PMID 40404986, 2025). "While CD40 is known to activate non-canonical NF-κB signaling component RelB, which has been shown to control BCLXL expression in related hematological malignancies, the control of MCL1 by specific NF-κB subunits is less clear, particular in the context of lymphoma." (PMID 40819126, 2025). "Indeed, analysis of lysates from 13 lymphoma patients revealed a significant inverse correlation between Mcl-1 and SOD1 protein levels in vivo, validated by Pearson correlation analysis." (PMID 40707672, 2025). "In addition, we observed that the Mcl-1 expression was significantly reduced when ixazomib was combined with venetoclax, similarly to what was observed for the lymphoma models (right)." (PMID 40701968, 2025). "It is well known that Bcl-2 and Mcl-1 are proteins that are overexpressed in lymphomas." (PMID 39769118, 2024).